PIK3CA (phosphatidylinositol-4,5-bisphosphate 3-kinase catalytic subunit alpha)
Diseases named in the same sentence as PIK3CA in open-access papers (continued):
Sharing a sentence is not in itself a finding about the gene and the disease.
tumor (continued). "This dual-targeting strategy effectively suppressed PIK3CA-mutated tumor growth and epithelial-mesenchymal transition." (PMID 41281644, 2025). "Advanced‐stage tumours exhibited higher frequencies of PIK3CA (47.8% vs. 19.4%, p = .026) and PTEN mutations (26.1% vs. 3.2%, p = .034)." (PMID 40817602, 2025). "When mutated, PIK3CA can drive tumor progression, increase invasiveness, and contribute to treatment resistance." (PMID 40949797, 2025). "In hepatocellular carcinoma, aberrant activation of the PI3K/AKT/mTOR pathway—often due to PIK3CA mutations—is closely associated with aggressive tumor behavior and poor clinical outcomes." (PMID 41133538, 2025). "Given the established association between PIK3CA mutations and tumor aggressiveness, rigorous clinical surveillance, along with the exploration of targeted therapies and potential immunotherapeutic approaches, is strongly warranted." (PMID 41133538, 2025). "Mutations in PIK3CA lead to aberrant activation of this pathway, promoting tumor cell proliferation and survival." (PMID 40936705, 2025). "For example, the presence of PIK3CA mutations is associated with a more aggressive tumor phenotype, which can be visualized as increased metabolic activity on PET scans." (PMID 40075655, 2025). "Tumor cells often depend on constitutively active PI3K/AKT signaling due to genetic alterations such as PTEN loss or PIK3CA amplification, rendering them more vulnerable to inhibitors targeting this axis." (PMID 41270054, 2025). "PIK3CA mutations affect a variety of biological properties of tumor cells, including some essential metabolic features, profiles of secreted immunocytokines, regulation of the cell cycle, formation of tolerance to polyploidy and chromosomal instability, etc.." (PMID 40507317, 2025). "SNVs in PIK3CA were more heterogeneous and occurred randomly distributed within each tumor, with some samples harboring multiple variants." (PMID 40489430, 2025). "Abnormal activation of the PI3K/AKT/mTOR signaling pathway due to mutations in PIK3CA can promote tumor growth, angiogenesis, and resistance to apoptosis." (PMID 39744583, 2025). "To investigate the relationship between PIK3CA mutation and tumor-infiltrating immune cells in the NSCLC microenvironment, we utilized the TIMER database for immune cell infiltration analysis." (PMID 40328748, 2025). "No patient was found to have a mutation in ESR1 in the primary tumor sample, while ~12% were identified with PIK3CA mutations." (PMID 40076662, 2025). "Western blot and IHC results revealed that compared to the wild-type group, tumor specimens from mice carrying the PIK3CA-E545K point mutation exhibited higher levels of PD-L1 protein and less infiltration of CD8+ T cells." (PMID 40328748, 2025). "Meanwhile, NGS of ctDNA can detect actionable mutations (e.g., those in BRCA2, AR, and PIK3CA) and track tumor burden over time." (PMID 40427518, 2025). "For LUSC, one interpatient tumor pair was misclassified as clonal for which identical PIK3CA-G1624A mutations were detected." (PMID 40373350, 2025). "Multifocal tumors with PIK3CA mutations exhibit variable drug responses, emphasizing the necessity for comprehensive genomic analysis across multiple tumor regions to refine treatment strategies." (PMID 40628732, 2025). "Utilizing genetic profiling to tailor treatments based on specific mutations, such as PIK3CA mutations, ensures that patients receive the most effective therapies for their unique tumor characteristics." (PMID 39953539, 2025). "Advanced‐stage tumours showed higher frequencies of preoperative ctDNA‐positive PIK3CA and PTEN mutations, suggesting their role in disease progression." (PMID 40817602, 2025). "Studies have shown that PIK3CA mutations not only promote tumor growth and metastasis but also correlate closely with immune evasion and resistance to immune checkpoint inhibitors (ICIs)." (PMID 40328748, 2025).
tumor (continued). "Among the genetic alterations affecting this pathway, activating mutations in PIK3CA are implicated in promoting uncontrolled cell proliferation and tumor progression." (PMID 40666093, 2025). "The next-generation sequencing (NGS) analysis of the tumor identified a PIK3CA mutation and a tumor mutational burden (TMB) of 6.17 mutations per megabase." (PMID 40909965, 2025). "Liquid biopsy by circulating tumor DNA (ctDNA) analysis offers a promising alternative to traditional tissue biopsy methods for detecting PIK3CA mutations, thereby enhancing minimally invasive patient monitoring and treatment selection." (PMID 40050490, 2025). "They assessed ctDNA at treatment initiation and completion using a targeted amplicon panel for tumor purity evaluation and ddPCR for PIK3CA/ESR1 mutation detection." (PMID 40050490, 2025). "In this context, confirming a PIK3CA mutation in tumor tissue supports the use of the PI3K inhibitor alpelisib to improve disease control and overcome endocrine resistance, exemplifying the principles of precision oncology." (PMID 40909965, 2025). "In this study, the authors found that PIK3CA mutation is closely related to tumor quadrants, histological subtypes, advanced clinical stage, tumor perineural invasion and high NLR." (PMID 40472482, 2025). "Here, we discuss how PIK3CA mutations rewire cell signaling, metabolism, and tumor microenvironment, as well as therapeutic strategies that are under development to treat patients with tumors harboring a PIK3CA mutation." (PMID 39717717, 2025). "Our previous work demonstrated that alpelisib, an effective anti-tumor agent, can reverses PIK3CA mutation-driven MDSCs recruitment." (PMID 41281644, 2025). "Studies on PIK3CA mutations and tumor lipid metabolism reveal that the PIK3CA-E545K mutation promotes nuclear accumulation of SREBP1, enhancing transcription of apolipoprotein A5 (APOA5) and thereby mediating platinum-based drug resistance in CRC." (PMID 40718481, 2025). "Literature research also confirms this point, and mutations at the E545K site of PIK3CA are known to lead to tumor drug resistance." (PMID 40328748, 2025). "In squamous cervical carcinomas, PIK3CA mutations correlate with a higher tumor mutation burden and increased mutations in other cancer-associated pathways." (PMID 40647429, 2025). "Patients with hyperglycolytic CRC subtypes (CMS3), KRAS or PIK3CA mutations, or tumours featuring M2 macrophage infiltration would likely benefit most from such strategies." (PMID 41399129, 2025). "Nevertheless, several factors such as age, tumor size, incomplete resection, or certain genetic mutations have been blamed for negatively influencing survival, e.g., a mutation on PIK3CA along with intratumoral calcifications was linked to worse prognosis." (PMID 40143126, 2025). "This showed that ~6% of the tumours with mutations in PIK3CA also had mutations, truncations, or homozygous deletions in PTEN." (PMID 40263319, 2025). "Deleterious mutations in the tumor-suppressor PTEN mimic activating mutations in the oncogene PIK3CA, both driving elevated intracellular levels of PIP3 and promoting oncogenic signaling." (PMID 40991650, 2025). "While an exploratory analysis of circulating tumor DNA suggested that the presence of an ESR1 or PIK3CA mutation negated any benefit from adding ribociclib, these were small and post hoc analyses." (PMID 41226406, 2025). "As a significant boost for personalized BC care, the FDA now allows testing for PIK3CA mutations, which are found in 30–40% of patients, using both tumor tissue and blood-based circulating tumor DNA (ctDNA)." (PMID 40050490, 2025). "It is notable that 80% of tumor tissues collected to generate PDOs with PIK3CA mutations also harbored KRAS mutations." (PMID 39808497, 2025).
tumor (continued). "For instance, one study comparing comprehensive genotyping found about 77% overall agreement between tissue DNA and ctDNA for PIK3CA mutations, rising to 95% concordance in patients with a ctDNA tumor fraction ≥ 2%." (PMID 40507825, 2025). "Recent multi-omics analysis of gastric adenocarcinoma has also identified an ‘Inflamed’ tumor subgroup with PIK3CA mutations showing distinct immune signaling properties in the tumor microenvironment." (PMID 40595500, 2025). "The 3 most common PIK3CA variants described in the literature are E545K and E542K in the helical domain, and H1047R in the kinase domain, across tumor types, which is concordant with our sample findings." (PMID 39401325, 2024). "Compared with wild-type PIK3CA, mutated PIK3CA was shown to promote the proliferation and migration of tumor cells." (PMID 38616230, 2024). "The most prevalent solid tumour mutation was PIK3CA H1047R, which was detected in tumour samples from 6 participants and was 1 of just 2 plasma variants found in more than 1 participant (each was detected in 2 participants)." (PMID 38182588, 2024). "As more feline oncogenomic studies are performed, additional tumour types will undoubtedly have PIK3CA alterations (mutations or amplifications)." (PMID 38787171, 2024). "The concordance rate between the detection of the PIK3CA (H1047R) mutation in tumor tissue and plasma samples was 84.2% (32 out of 38 cases), with a Cohen’s κ coefficient of 0.661 (95% CI, 0.412–0.910)." (PMID 39462049, 2024). "Direct comparison between the ultrasensitive real-time PIK3CA PCR assay and the ddPCR PIK3CA mutation test for PIK3CA p.E545K, p.E542K and p.H1047R mutations in 42 primary tumor samples (FFPEs)." (PMID 39711963, 2024). "Immunohistochemistry, on the other hand, detects protein expression related to PIK3CA mutations, providing functional insights into tumor biology." (PMID 39555098, 2024). "The presence of these mutations alongside PIK3CA mutations in NSCLC can lead to more aggressive tumor behavior and increased resistance to treatment." (PMID 39685930, 2024). "The close molecular relationship between PTEN and PIK3CA explains similar clinical manifestations in mutations of these genes, with tumor development in the breast or thyroid, as described." (PMID 39336800, 2024). "These tumours were also analysed for the mutational spectrum of the cancer driver genes and this analysis showed a significant mutation load of PIK3CA in mir-18a/low tumours when compared to mir-18a/high tumours (p = 2.15 × 10−5 and odds ratio: 8.71 × 10−2)." (PMID 38786043, 2024). "While PIK3CA mutations are strongly associated with lymph node metastasis and increased tumor invasiveness, PIK3C2G, another key PI3K family member, has emerged as a potential tumor suppressor." (PMID 39950101, 2024). "Firstly, PIK3CA gene mutation itself is a new tumor antigen that can be recognized and attacked by the immune system." (PMID 39555098, 2024). "Analyzing the tumor's genetic profile, particularly PIK3CA mutations, will allow healthcare providers to individualize treatment decisions and select the most appropriate treatment option." (PMID 38172946, 2024). "They reported that alterations in the PIK3CA gene (mutations and copy gains) were associated with a reduced probability of tumour recurrence." (PMID 39768623, 2024). "In the preclinical tumor cell line model, Nicolantonio and colleagues observed drug insensitivity in the co-mutation of PIK3CA and KRAS." (PMID 39056802, 2024). "A few studies have shown that tumor cells harboring PIK3CA mutations are more sensitive to inhibitors targeting the PI3K signaling pathway." (PMID 38616230, 2024).
tumor (continued). "Liquid biopsy, which analyzes circulating tumor DNA (ctDNA) or circulating tumor cells (CTCs) in blood, provides a non-invasive approach to assess PIK3CA mutations and monitor treatment response." (PMID 38172946, 2024). "We also found similar PIK3CA mutation rates between these two tumor groups in our study, consistent with results previously reported by Denkert and collaborators." (PMID 38893129, 2024). "PIK3CA amplifications were exclusively found in tumours that harboured PIK3CA gain-of-function mutations affecting the H1047R and E542K residues." (PMID 39322687, 2024). "For example, KRAS and PIK3CA mutations exist within the same tumor; conversely, KRAS and BRAF mutations are mutually exclusive." (PMID 39056802, 2024). "Phosphoinositide 3-kinases (PI3Ks) play an important role in tumor development and progression, and recurrent activating mutations in the p110 α subunit (PIK3CA) have been found in some tumors." (PMID 39160638, 2024). "The concordance rate between the detection of the PIK3CA (H1047R) mutation in tumor tissue and serum samples was 83.3% (35 out of 42 cases), with a Cohen’s κ coefficient of 0.581 (95% CI, 0.305–0.857)." (PMID 39462049, 2024). "Upon primary testing using a specific commercial dPCR probe, the presence of the PIK3CA mutation in tumor DNA was detected at a rate of 86.1%, whereas in genomic DNA, the mutation was detected at a rate of 0.03%." (PMID 39596073, 2024). "If the tumor presents with high mutation abundance PIK3CA mutations after Osimertinib resistance, patients will potentially benefit from PIK3CA inhibitor therapy." (PMID 39160638, 2024). "Half (50%) of the patients carried a PIK3CA mutation either in the primary or relapse tumor and the mutational frequency was higher in the relapse setting (48%) than in the primary (40%)." (PMID 38822093, 2024). "PIK3CA mutations are most frequently found in ER-positive tumours and has a strong correlation with estrogen receptor signalling." (PMID 38786043, 2024). "Among the PIK3CA mutation-positive tumor samples with AKT data (CB n = 7, NCB n = 5), the amount of AKT present per 10 μg total protein ranged from 0.6 to 4.5 fmol for AKT1 and 0.6 to 2.0 fmol for AKT2." (PMID 38954770, 2024). "The potential underlying mechanism is that the PIK3CA H1047R mutation is a stronger driver of tumor development than other types of PIK3CA mutations." (PMID 38344201, 2024). "In patients with advanced hormone receptors (HR)+/HER2-negative BC, 28% of PIK3CA mutations were identified in circulating tumor DNA." (PMID 38344201, 2024). "In MT high‐TME low subgroup, tumour mutations were identified in 68 of 85 samples (80%), including PIK3CA (27%), TTN (26%) and KMT2C (21%)." (PMID 38534098, 2024). "Increased APOA5 expression was associated with PIK3CA mutation in tumor specimens and poor response to first-line chemotherapy, which was an independent detrimental factor for chemotherapy sensitivity in CRC patients." (PMID 38848145, 2024). "Lastly, the influence of PIK3CA gene mutations on the tumor microenvironment (TME) includes both vascular and immune modulation." (PMID 39555098, 2024). "Then, we analyzed expression profiles for each of the three pathways according to the presence of an activating PIK3CA mutation, but independently of the tumor HER2 status." (PMID 38893129, 2024). "The PIK3CA is a tumour-specific gene that encodes type IA P13K protein to activate the P13K/Akt/mTOR signalling pathway in promoting cell proliferation." (PMID 38245692, 2024).
tumor (continued). "Tumor cells with a PIK3CA mutation and LGR5 expression exhibit poor sensitivity to first-line chemotherapy in vitro." (PMID 38892410, 2024). "In preclinical models, Alpelisib exhibited robust inhibitory efficacy against cancer cell lines characterized by PIK3CA mutations, alongside its capacity to diminish tumor progression within xenograft models harboring PIK3CA mutations." (PMID 38474678, 2024). "Analysis of approximately 80,000 tumor samples from 224 studies (cBioportal) reveals that 10.2% and 6.2% samples bear mutations in PIK3CA and PTEN, making these the most frequently mutated PI3K genes." (PMID 39796708, 2024). "The average tumour-free survival was significantly longer in cases with mutations in the PIK3CA gene (p = 0.02), and mutations in the PIK3CA gene were associated with a decreased risk of tumour recurrence (Hazard Ratio = 0.26; 95% CI: 0.11–0.62; p = 0.018)." (PMID 39768623, 2024). "For instance, p110α is important in the signaling and tumor growth driven by PIK3CA mutations and/or oncogenic receptor tyrosine kinases, whereas p110β isoform is essential in mediating tumorigenesis arising from PTEN loss." (PMID 38396649, 2024). "The most often found mutant oncogene throughout tumor lineages is the PIK3CA activating mutation, which encodes the p110α catalytic subunit of PI3K." (PMID 39062182, 2024). "In the relapse setting, the associations were also statistically significant when comparing PIK3CA mutations in the relapse tumor to the nodal status and pN status in the primary tumor setting (p = 0.0056 and p = 0.0064, respectively)." (PMID 38822093, 2024). "Several small-molecule inhibitors targeting the PI3K protein have also demonstrated efficacy in inducing tumor regression in cells harboring PIK3CA mutations." (PMID 38671743, 2024). "The detection of the PIK3CA-H1047R variant is of paramount importance due to its close association with tumor growth and treatment resistance." (PMID 39070168, 2024). "Of these, the hotspot mutation at PIK3CA H1047R was most common, identified in 17% (27/158) of tumours." (PMID 38812774, 2024). "Non-hotspot mutations were common, and even more so in primary tumors (29% in either tumor, 35% in primary and 31% in relapse tumors of patients with PIK3CA mutations)." (PMID 38822093, 2024). "Consistently, activating mutations in PIK3CA are identified in 11% of LGSOC tumours, and inactivating PTEN mutations occur in 20% of cases, suggesting that PI3K pathway inhibition can become a central target in LGSOCs." (PMID 38785992, 2024). "Mutations in PIK3CA, especially at hotspots like E542K, E545K, H1047R and H1047L, have been correlated with aggressive tumor behavior, recurrence and metastatic spread in endometrial cancer, breast cancer, cervical cancer and colorectal cancer." (PMID 38832948, 2024). "The PI3K/AKT/mTOR pathway is particularly significant, with mutations in PIK3CA commonly associated with venous and lymphatic malformations but can be also found in tumour endothelial cells." (PMID 39608012, 2024). "Other genes that have been proven to be associated with tumor initiation or progression like PIK3CA, ATM, PTEN, and CREBBP are also present in PDTC and ATC with a mutation frequency higher than 5%." (PMID 39235852, 2024). "Another study utilized circulating tumor DNA (ctDNA) detection technology and found that the detection of PIK3CA gene mutations in ctDNA was associated with worse OS and PFS, independent of treatment regimens." (PMID 39555098, 2024).